CCDC170 (coiled-coil domain containing 170)
Diseases named in the same sentence as CCDC170 in open-access papers (continued):
Sharing a sentence is not in itself a finding about the gene and the disease.
osteoporosis (4 papers, 2021 to 2023). A condition of reduced bone mass, with decreased cortical thickness and a decrease in the number and size of the trabeculae of cancellous bone (but normal chemical composition), resulting in increased fracture incidence. "In a follow-up study, CCDC170 polymorphisms were in turn associated with osteoporosis-relevant phenotypes." (PMID 34066823, 2021). "The present work focused largely on identifying a potential molecular mechanism for CCDC170-associated osteoporosis risk and progression." (PMID 33785515, 2021). "GWAS studies in humans have reported an association of the CCDC170 gene with bone mineral density, while other studies have confirmed the role of CCDC170 in osteoporosis or hip fractures." (PMID 37144137, 2023). "Our study provides a possible mechanism for this finding, in that upregulation of miR-153-3p, miR-374b-3p, miR-4274, miR-572 and miR-2964a-5p resulted in decreased CCDC170 expression in osteoporosis." (PMID 33785515, 2021). "In summary, we found a new function of CCDC170 in bone biology and five new miRNAs that promote the development of osteoporosis, providing new options and targets for the treatment of osteoporosis." (PMID 33785515, 2021). "In order to investigate the role of CCDC170 and explore the relationship between miRNA, SNPs and CCDC170 in osteoporosis, we performed a series of gene overexpression and knockdown experiments in cells and mice vivo." (PMID 33785515, 2021).
lymph node metastasis (2 papers, 2022 to 2024). "The results showed that the expression of lnc-CCDC170–4:1 was associated with lymph node metastasis (p=0.030)and Tumor size(p=0.047), Low expression of ESR was associated with FIGO Staging(p=0.041)and Tumor size(p=0.002)." (PMID 39206151, 2024). "Low expression of lnc-CCDC170–4:1 was associated with lymph node metastasis (p=0.030) and Tumor size (p=0.047), Low expression of ESR was associated with FIGO Staging (p=0.041)and Tumor size(p=0.002),High expression of LncSRA was associated with FIGO Staging(p=0.004)." (PMID 39206151, 2024). "Low expression of lnc-CCDC170–4:1 and ESR1 are associated with lymph node metastasis and FIGO stage, so it may be a potential biomarker to evaluate the prognosis of cervical cancer." (PMID 39206151, 2024). "Moreover, low expression of lnc-CCDC170–4:1 and ESR1 are associated with lymph node metastasis and FIGO stage, so it may be a potential biomarker to evaluate the prognosis of cervical cancer." (PMID 39206151, 2024).
cervical cancer (1 paper, 2024). A primary or metastatic malignant neoplasm involving the cervix. "In this study, we investigated the role of ESR1 and its corresponding lnc-CCDC170–4:1 in cervical cancer." (PMID 39206151, 2024). "We found that the relative expression levels of lnc-CCDC170–4:1 and ESR mRNA were significantly lower in cervical cancer tissue than in the control (P<0.05)." (PMID 39206151, 2024). "The expressions of lnc-CCDC170–4:1, ESR1, lncRNA SRA, and CYP19A1 were validated in 26 cases of cervical cancer tissue and 30 cases of normal cervical tissue using qRT-PCR." (PMID 39206151, 2024). "The expression levels of lnc-CCDC170–4:1, ESR, lncRNA SRA, and CYP19A1 were validated using qRT-PCR in 26 cases of cervical cancer tissue and 30 cases of normal cervical tissue." (PMID 39206151, 2024). "In conclusion, the expression of lncRNA SRA and CYP19A1 is elevated in cervical cancer, while lnc-CCDC170–4:1 and ESR1 expression is decreased in cervical cancer." (PMID 39206151, 2024). "Therefore, the lnc-CCDC170–4:1 and ESR1 may be an important factor for evaluating the prognosis of cervical cancer, and their specific mechanism of action in cervical cancer is also one of our main research directions in the future." (PMID 39206151, 2024).
cervical squamous cell carcinoma (1 paper, 2024). A squamous cell carcinoma arising from the cervical epithelium. "The expression levels of CYP19A1 and lncRNA SRA were upregulated, while those of ESR1 and lnc-CCDC170–4:1 were downregulated in cervical squamous cell carcinoma tissue." (PMID 39206151, 2024). "This study investigated the expression of lnc-CCDC170–4:1, ESR1 (estrogen receptor 1), lncRNA SRA, and CYP19A1 (aromatase) in cervical squamous cell carcinoma tissues, as well as their relationship with the clinical characteristics of patients." (PMID 39206151, 2024).
gynecologic cancer (1 paper, 2026). "Whole transcriptome sequencing detected ESR1 fusion genes in 2.1% (n = 55/2574) of BC samples and in 1.9% (n = 21/1110) of gynecologic cancer samples, and CCDC170 was the most common fusion partner in both cancer types." (PMID 41555446, 2026).
ovarian carcinoma (1 paper, 2023). A malignant neoplasm originating from the surface ovarian epithelium. "CCDC170 is expected to become a new diagnostic molecular target and prognostic indicator for ovarian cancer patients, which can provide new ideas for the design of antitumor drugs." (PMID 37024829, 2023). "CCDC170 was the most significantly associated gene with ovarian cancer prognosis (p < 0.001)." (PMID 37024829, 2023). "It was first reported that CCDC170 copy number variation can reduce its expression, thereby affecting the overall survival of patients with ovarian cancer, and it is a pathogenic mutation of ovarian cancer." (PMID 37024829, 2023). "At the same time, the expression of CCDC170 in ovarian cancer tissues was significantly lower than that in normal tissues." (PMID 37024829, 2023). "In our Western blotting results, the expression of CCDC170 in ovarian cancer cell lines was significantly lower than that in normal ovarian cells." (PMID 37024829, 2023). "CCDC170 can be used as a new promising molecular target for ovarian cancer patients, which is related to the good prognosis of the protein." (PMID 37024829, 2023). "At the same time, the expression of CCDC170 in patients with advanced ovarian cancer was lower than that in patients with early ovarian cancer." (PMID 37024829, 2023). "The expression of CCDC170 in ovarian cancer cell lines 3AO and ES2 was significantly lower than that in IOSE-80 (P < 0.001, P < 0.001)." (PMID 37024829, 2023). "The prognosis of ovarian cancer patients was significantly improved when the CCDC170 gene was highly expressed." (PMID 37024829, 2023). "The expression of CCDC170 in normal tissues was significantly higher than that in ovarian cancer tissues (P < 0.05), and its expression was significantly decreased in advanced ovarian cancer." (PMID 37024829, 2023). "As a newly discovered downregulated molecular target of ovarian cancer, CCDC170 can provide a new direction for the development of agonists to reverse the treatment of ovarian cancer." (PMID 37024829, 2023). "In particular, the overall survival of ovarian cancer patients with high CCDC170 gene expression was significantly prolonged (P < 0.001)." (PMID 37024829, 2023). "Western blotting and immunofluorescence assays also showed that the expression of CCDC170 in ovarian cancer cells was significantly lower than that in normal cells (P < 0.001, P < 0.01)." (PMID 37024829, 2023). "In addition, we also used TCGA data to detect the expression of COL14A1, THBS2 and CCDC170 genes in different stages of ovarian cancer patients." (PMID 37024829, 2023). "In the three ovarian cancer cohorts, only copy number variation of the CCDC170 gene occurred." (PMID 37024829, 2023). "In addition, the expression of COL14A1 and THBS2 was significantly increased in ovarian cancer cell lines compared to normal ovarian cells (P < 0.05, P < 0.01), but the differential expression in CCDC170 was the opposite." (PMID 37024829, 2023). "This indicates that CCDC170, COL14A1 and THBS2 are expected to become targets for the diagnosis and treatment of ovarian cancer." (PMID 37024829, 2023). "We verified the expression of CCDC170, THBS2 and COL14A1 in ovarian cancer cells by Western blotting (WB) and immunofluorescence assay (IF)." (PMID 37024829, 2023). "The differential expression of CCDC170, MTRF1L, ZBTB2, ARMT1, PLEKHG1 and QRSL1 genes affected the overall survival (OS) of ovarian cancer patients." (PMID 37024829, 2023). "Similarly, although THBS2 and COL14A1 also showed differential expression in ovarian cancer cell lines and normal ovarian cells, the results were not as significant as those for CCDC170." (PMID 37024829, 2023).
ovarian tumor (1 paper, 2020). "One additional ovarian tumor harbored the same fusion, although induction of CCDC170 was not significant (p = 0.44)." (PMID 33097743, 2020).
tumor (14 papers, 2011 to 2025). "The possible reason is that the expression of CCDC170 in the cytoplasm of tumor cells is inhibited, leading to tumor progression." (PMID 37024829, 2023). "Based on these results, CCDC170 fusion-positive BRCA patients have distinct pathological characteristics in terms of tumor subtype and triple positive tendency." (PMID 33557149, 2021). "Combined with our initial observation that CCDC170 overexpression mainly induced genes involved in apoptosis, these results suggested that CCDC170 is a tumor inhibitor." (PMID 33291081, 2020). "We also analyzed the associations of CCDC170, IRE1 and XBP1 mRNA levels with clinicopathologic characteristics such as ERα, progesterone receptor (PR), Her2 and Ki67 levels, the PAM50 subtype, tumor size, lymph node status and TNM stage in TCGA and GEO." (PMID 33291081, 2020). "However, it has been proposed that CCDC170 can function as either an oncogene or a tumor suppressor." (PMID 33291081, 2020). "Indeed, overexpression of the C-terminal truncated CCDC170 protein, which originates from a translocation between ESR1 and CCDC170, increased the migration ability of tumor cells." (PMID 30149579, 2018). "Note that CCDC170, but not ESR1, mRNA levels were significantly higher in these normal (adjacent to tumor) tissues than in cancer tissue (Kruskal Wallis Test P < 0.0001." (PMID 35151276, 2022).
cancer (10 papers, 2009 to 2026). A tumor composed of atypical neoplastic, often pleomorphic cells that invade other tissues. "The fusion between ESR1 and its neighboring gene CCDC170 are potentially generated by tandem duplication, which is also causing other genetic rearrangements in cancer." (PMID 35151276, 2022). "In the six major cancer-related pathways, 137 genes were significantly over- or under-expressed in the CCDC170 fusion-positive cases compared with the CCDC170 fusion-negative controls." (PMID 33557149, 2021). "Other genes within this cluster include CCDC170, WNK4 and AGR3 which have been reported to be implicated in these cancers." (PMID 30279965, 2018). "CCDC170 is also expected to become a therapeutic target in cancer." (PMID 33291081, 2020). "Thus, ESR1 and CCDC170 fusion transcript pinpoint cancers with an adverse outcome." (PMID 35151276, 2022).
CCDC170 also shares sentences with these, for which no sentence is quoted: acute myeloid leukemia (1 paper); Fibroadenoma (1); fractures (1); invasive ductal carcinoma (1); metastatic tumor (1); triple-negative breast carcinoma (1); type 1 diabetes (1); xeroderma pigmentosum (1).